AKR1B10 (aldo-keto reductase family 1 member B10)
Description:
Catalyzes the NADPH-dependent reduction of a wide variety of carbonyl-containing compounds to their corresponding alcohols. Displays strong enzymatic activity toward all-trans-retinal, 9-cis-retinal, and 13-cis-retinal. Plays a critical role in detoxifying dietary and lipid-derived unsaturated carbonyls, such as crotonaldehyde, 4-hydroxynonenal, trans-2-hexenal, trans-2,4-hexadienal and their glutathione-conjugates carbonyls (GS-carbonyls). Displays no reductase activity towards glucose.
Synonyms: AKR1B11; AKR1B12; ARL-1; HIS; ARL1; HSI; ALDRLn
Tractability: Small molecule: a structure with a bound ligand is known; a high-quality ligand is known; it has a high-quality binding pocket; it belongs to a druggable protein family. Antibody: UniProt places it where antibodies can reach, with high confidence; its Gene Ontology location is reachable by antibodies, with high confidence; the Human Protein Atlas places it where antibodies can reach. PROTAC: ubiquitination databases record sites on it; its protein half-life has been measured; a small molecule that binds it is known.
Target class: Enzyme; Oxidoreductase
Chemical probes: CHEMBL1940400
Gene: Protein-coding gene on chromosome 7 (134,527,567 to 134,541,412, forward strand). Ensembl gene ENSG00000198074.
Subcellular location: Lysosome; Secreted
Subcellular location (Human Protein Atlas): Cytosol; Plasma membrane; Predicted to be secreted
Pathways (Reactome):
Sensory Perception: Retinoid metabolism and transport
Gene Ontology:
Molecular function: alcohol dehydrogenase (NADP+) activity; all-trans-retinol dehydrogenase (NADP+) activity; allyl-alcohol dehydrogenase activity; indanol dehydrogenase activity; oxidoreductase activity, acting on the CH-OH group of donors, NAD or NADP as acceptor; protein binding; retinal dehydrogenase (NAD+) activity; aldose reductase (NADPH) activity; oxidoreductase activity
Biological process: cellular detoxification of aldehyde; daunorubicin metabolic process; doxorubicin metabolic process; farnesol catabolic process; retinoid metabolic process; lipid metabolic process; retinol metabolic process
Cellular component: cytosol; extracellular region; lysosome; mucus layer; plasma membrane; mitochondrion
Genetic constraint (gnomAD): Loss-of-function variants: 38 observed, 37.62 expected, observed/expected ratio (o/e) 1.01, 90% interval 0.78 to 1.32. The upper end of that interval is the gene's LOEUF score, 1.32, which puts it in group 5 of 6, group 1 being the genes least tolerant of losing a copy. Missense variants: 351 observed, 373.13 expected, observed/expected ratio (o/e) 0.94, 90% interval 0.86 to 1.03. Synonymous variants: 147 observed, 138.49 expected, observed/expected ratio (o/e) 1.06, 90% interval 0.93 to 1.22.
Homologues: Orthologues: chimpanzee AKR1B10 (99% identical), macaque AKR1B10 (87% identical), rabbit AKR1B10 (86% identical), mouse Akr1b10 (83% identical), rat Akr1b8 (83% identical), mouse Akr1b8 (82% identical), rat Akr1b10 (82% identical), mouse Akr1b7 (80% identical), rat Akr1b7 (73% identical), zebrafish akr1a1a (53% identical), Drosophila melanogaster CG6083 (46% identical), zebrafish zgc:56622 (44% identical), and 17 more. Paralogues in human: AKR1B15 (86% identical), AKR1B1 (71% identical), AKR1E2 (56% identical), AKR1D1 (52% identical), AKR1A1 (49% identical), AKR1C2 (49% identical), AKR1C4 (49% identical), AKR1C1 (49% identical), AKR1C8 (49% identical), AKR1C3 (48% identical), KCNAB1 (27% identical), KCNAB2 (27% identical), and 4 more.
Diseases named in the same sentence as AKR1B10 in open-access papers:
AKR1B10 is named in the same sentence as 129 diseases in open-access papers, as found by Europe PMC text mining. Sharing a sentence is not in itself a finding about the gene and the disease. The quoted sentences say what the papers report.
hepatocellular carcinoma (45 papers, 2012 to 2026). A malignant tumor that arises from hepatocytes. "Whilst AKR1B10 has been associated with hepatocellular carcinoma, its co-localisation within cells containing polymers suggests an association of this protein with A1ATD." (PMID 29879455, 2018). "The detoxification enzyme AKR1B10 is a well-known aldo-keto reductase family member that has been linked to hepatocellular carcinoma and proposed as a new possible biomarker and an independent risk factor." (PMID 30125264, 2018). "Previous studies have reported that the aberrantly expressed AKR1B10 is associated with many cancer development, however the functional roles of AKR1B10 and its regulatory mechanisms in hepatocellular carcinoma (HCC) have been limited studied." (PMID 30038373, 2018). "With regard to infectious diseases, AKR1B10 is overexpressed in hepatitis B and C and is linked to the development of hepatocellular carcinoma." (PMID 30320113, 2018). "AKR1B10 is also upregulated in hepatocellular carcinoma and serves as a diagnostic marker." (PMID 35280770, 2022). "In hepatocellular carcinoma (HCC), an increased expression of AKR1B10 is associated with poor prognoses, indicating its potential role in promoting tumor survival." (PMID 38931461, 2024). "The presence of AKR1B10 may therefore be a direct consequence of polymerised protein accumulation, characterising a subset of hepatocytes primed towards malignancy, making AKR1B10 a potential tissue biomarker for hepatocellular carcinoma risk stratification." (PMID 29879455, 2018). "As an inflammatory regulator in HCC, AKR1B10's influence on the immune microenvironment of hepatocellular carcinoma was further studied." (PMID 38802416, 2024). "The results indicated that although AKR1B10 is highly expressed in various tumors, it significantly affects the prognosis of hepatocellular carcinoma patients only." (PMID 38802416, 2024). "To further understand the biological function of AKR1B10 in hepatocellular carcinoma, we used the LinkRank module on the LinkedOmics website to detect the co-expression pattern of AKR1B10 in LIHC within the TCGA database." (PMID 38802416, 2024). "To better understand the mechanism of action of AKR1B10 in the development and progression of hepatocellular carcinoma, we used three databases, miRDB, miRWalk, and Targetscan, to predict upstream miRNAs of AKR1B10." (PMID 38802416, 2024). "Based on the median expression level of AKR1B10 mRNA, hepatocellular carcinoma patients from the TCGA-LIHC cohort were divided into high and low expression groups for correlation analysis with clinicopathological features." (PMID 38802416, 2024). "Increasing evidences have indicated that AKR1B10 takes part in the acquirement of chemo-resistance in several cancers, including hepatocellular carcinoma(HCC), gastrointestinal cancer and lung cancer." (PMID 37587486, 2023). "AKR1B10 is a member of the AR superfamily and has been identified as a novel protein in human hepatocellular carcinoma (HCC)." (PMID 37587486, 2023). "In particular, the up-regulated AKR1B10 was reported to exert a protective role by eliminating oxidative stress and was identified as a biomarker in older hepatocellular carcinoma patients." (PMID 35752290, 2022). "Aldo-keto reductase 1B10 (AKR1B10) is a secretory protein that is primarily expressed in human colon and small intestine, but induced in hepatocellular carcinoma (HCC), pancreatic cancer, and non-small cell lung cancer." (PMID 35280770, 2022). "AKR1B10P1 is the pseudogene of oncogene AKR1B10 in hepatocellular carcinoma, noticed as being anomalistic transcribed preliminarily." (PMID 34552036, 2021). "Recently, AKR1B10 was reported to be overexpressed in a wild range of cancers, including hepatocellular carcinoma, breast cancer, pancreatic carcinoma, and lung cancer." (PMID 34035231, 2021).
hepatocellular carcinoma (continued). "In oral squamous cell carcinoma, non-small cell lung carcinoma and liver carcinoma, high expression levels of AKR1B10 in patients is correlated with poor prognosis." (PMID 34419144, 2021). "This study provided the first evidence that AKR1B10 participates in hepatocellular carcinogenesis by regulating cell proliferation and apoptosis, and it can be used to identify hepatocellular carcinoma and benign liver lesions." (PMID 34521883, 2021). "For example, dysregulated expression of AKR1B10 in hepatocellular Carcinoma, breast cancer, and colorectal cancer make AKR1B10 inhibitors as potential drugs for cancer treatment." (PMID 34127944, 2021). "Overexpression of AKR1B10 correlated with tumorigenesis of many human malignancies; however, the prognostic value of AKR1B10 expression in patients with hepatocellular carcinoma (HCC) still remains controversial." (PMID 31598161, 2019). "In hepatocellular carcinoma, the expression of AKR1B10 is regulated through the activation of β-catenin signaling." (PMID 30320113, 2018). "Consistent with previous findings, AKR1B10 mRNA and protein levels were higher in primary hepatocellular carcinoma (PHC) tissues than in peri-tumor tissues." (PMID 26948042, 2016). "Recent clinicopathological studies demonstrate that AKR1B10 expression in hepatocellular carcinomas differs depending on the disease stage." (PMID 26949513, 2016). "Aldo-keto reductase 1 B10 (AKR1B10) is a multifunctional protein, identified primarily from human hepatocellular carcinoma (HCC)." (PMID 27248472, 2016). "This indicates that the expression of AKR1B10 in hepatocellular carcinoma is unstable." (PMID 38802416, 2024). "Thus, the specific mechanisms through which AKR1B10 affects the progression of hepatocellular carcinoma necessitate further elucidation via comprehensive basic experimental research, lending greater depth and validation to these preliminary findings." (PMID 38802416, 2024). "Similarly, overexpression of AKR1B10 was documented in hepatocellular carcinoma, breast, pancreatic, and lung cancer with significant downregulation in CRC." (PMID 39055885, 2024). "Further, previous evidence has uncovered that AKR1B10 may also participate in glycolysis in hepatocellular carcinoma and cholangiocarcinoma." (PMID 38671310, 2024). "Previous studies have established high expression of AKR1B10 in several cancers, including cholangiocarcinoma, hepatocellular carcinoma, lung adenocarcinoma, lung squamous cell carcinoma, prostate cancer, and uterine endometrial cancer, compared to adjacent normal tissues." (PMID 38802416, 2024). "Similarly, a recent study claimed that Fidarestat induces glycolysis of NK cells through decreasing AKR1B10 expression to inhibit hepatocellular carcinoma progression, especially lung metastasis." (PMID 37587486, 2023). "AKR1B10 is a secretory protein and regarded as potential serum marker of hepatocellular carcinoma." (PMID 32547320, 2020). "Hence, we assumed that AKR1B10 is emerging as a biomarker to distinguish hepatocellular carcinoma from benign liver lesions." (PMID 31598161, 2019). "To conclude, The high expression of AKR1B10 in hepatocellular carcinoma (HCC) is not only associated with significant clinical and pathological features but may also influence the progression and prognosis of HCC by activating key signaling pathways and altering the tumor immune microenvironment." (PMID 38802416, 2024). "AKR1B10 is also upregulated in hepatocellular carcinoma (HCC), but its role in progression and prognosis of HCC is controversial." (PMID 38370384, 2024). "more indirectly indicates that when the high expression of AKR1B10 promotes the occurrence of hepatocellular carcinoma, the number or activity of positive protective factors may increase synchronously in the early stage of the body, thus enhancing the body's ability to clear cells." (PMID 38802416, 2024).
hepatocellular carcinoma (continued). "Therefore, AKR1B10 may influence the biological processes of hepatocellular carcinoma through regulating the release of inflammatory factors and cellular metabolism, although the specific mechanisms still require validation through basic experimental research." (PMID 38802416, 2024). "Overexpression of AKR1B10 was first observed in hepatocellular carcinoma (HCC) and subsequently reported in a wide range of malignant cell lines and tumor tissues." (PMID 39055885, 2024). "In hepatocellular carcinoma (HCC), AKR1B10 expression is found upregulated, and experimental deletion of such gene inhibited the proliferation of HCC cells tumor growth in a xenograft mice model." (PMID 32097409, 2020). "In humans or rodents, AR and aldo-keto reductase family 1B10 (AKR1B10, also known as AR-like-1), were often among the most significantly up-regulated genes in many types of cancers including cervical cancer, colon cancer, leukemia, pancreatic cancer and hepatocellular carcinoma (HCC)." (PMID 28978011, 2017). "While AKR1B10 is highly up-regulated in malignancies such as hepatocellular carcinoma (HCC), pancreatic carcinoma, cholangiocarcinoma, lung cancer, and breast cancer, where it promotes oncogenesis and drug resistance, it is paradoxically down-regulated in gastrointestinal cancers." (PMID 40845116, 2025). "Furthermore, in patients with metabolic (dysfunction)-associated Steatohepatitis (MASH), high expression of hepatic AKR1B10 is linked to reduced hepatic retinoid levels, exacerbating the progression from MASH to Hepatocellular Carcinoma (HCC)." (PMID 38549744, 2024). "Therefore, we infer that the regulatory network DANCR-miR-216a-5p-AKR1B10 plays a role in hepatocellular carcinoma (HCC)." (PMID 38802416, 2024). "AKR1B10, which is also regulated by miRNA-383-5p, promotes hepatocellular carcinoma (HCC) progression and may be a therapeutic target for precision medicine." (PMID 37592783, 2023). "An additional study demonstrated that AKR1B10 and SPP1 were closely related to NAFLD and NAFLD-hepatocellular carcinoma immune cell infiltration and immunosuppressive cytokine expression." (PMID 36407083, 2022). "Aldo-keto reductase family 1, member B10 (AKR1B10), is primarily expressed in human colon and small intestine but overexpressed in breast cancer, hepatocellular carcinoma, non-small cell lung carcinoma, cervical and endometrial cancers." (PMID 28402270, 2017). "Using a co-culture system, we found that co-culture of QSG-7701 (human hepatocyte) with HepG2 (hepatoma cell line) increases QSG-7701’s proliferation, in which AKR1B10-S1P signaling plays a pivotal role." (PMID 26948042, 2016). "In summary, co-culture of QSG-7701 (human hepatocyte) with HepG2 (hepatoma cell line) increased QSG-7701’s proliferation, and this increase in proliferation is mediated by AKR1B10-S1P signaling." (PMID 26948042, 2016). "Aldo-keto reductase family 1, member B10 (AKR1B10), a cancer-related oxidoreductase, is expressed in well-differentiated hepatocellular carcinomas (HCCs)." (PMID 24747592, 2014). "Within this network, AKR1B10 was nominated as a PBC-critical gene, with clinical evidence demonstrating that its hepatic overexpression correlates with both disease severity and progression to hepatocellular carcinoma." (PMID 40832105, 2025). "AKR1B10, an NAD(P)H-dependent enzyme in the aldo-keto reductase family, plays a crucial role in the proliferation and metastasis of various malignancies, including hepatocellular carcinoma." (PMID 40777026, 2025). "AKR1B10 is a member of the aldo–keto reductase (AKR) superfamily that was identified as a novel protein correlated to the carcinogenesis of hepatocellular carcinoma (HCC), albeit the fact that the primary role of AKR1B10 is protecting gastrointestinal cells against carbonyl damage." (PMID 39001490, 2024).
hepatocellular carcinoma (continued). "Furthermore, AKR1B10 also participates in the carcinogenesis and tumor development through regulating EMT in gastric cancer, hepatocellular carcinoma and adrenocortical carcinoma cells." (PMID 38671310, 2024). "Furthermore, AKR1B10 and TYMS were upregulated in hepatocellular carcinoma patients compared to NAFLD." (PMID 38720280, 2024). "In patients with hepatocellular carcinoma (HCC), high expression of AKR1B10 is positively correlated with poor prognosis, indicating the protein may effect tumor survival." (PMID 34419144, 2021). "In this study, we found that co-culture of QSG-7701 (human hepatocyte) with HepG2 (hepatoma cell line) increases QSG-7701’s proliferation, and that AKR1B10-S1P signaling is necessary for this increase in proliferation; up-regulation of AKR1B10 and S1P levels was also confirmed in PHC tissues." (PMID 26948042, 2016). "Aldo-keto reductase 1B10 (AKR1B10), also known as aldose reductase-like-1 (ARL-1), is a secretory protein identified in human hepatocellular carcinoma (HCC) 6-8." (PMID 38370384, 2024). "AKR1B10 has been reported to be overexpressed in many non-digestive tract solid tumors such as non-small cell lung cancer in smokers, breast cancer, pancreatic cancer and hepatocellular carcinoma." (PMID 26949513, 2016). "Therefore, 11 paired tissues from hepatocellular carcinoma were obtained to determine AKR1B10 mRNA and protein expression levels side by side (data not shown), and we found that AKR1B10 mRNA and protein expression levels are not always consistent in a same patient." (PMID 26948042, 2016). "In our previous research on oncogene AKR1B10 in hepatocellular carcinoma (HCC), its pseudogene, AKR1B10P1, was preliminarily noticed being anomalistic transcribed, whereas whether AKR1B10P1 plays any specific function in HCC is poorly understood." (PMID 32924268, 2020).